BCL2 (BCL2 apoptosis regulator)
Diseases named in the same sentence as BCL2 in open-access papers (continued):
Sharing a sentence is not in itself a finding about the gene and the disease.
B-cell lymphoma (continued). "Conversely, if BCL2 intensity is moderate to strong and Ki-67 is <95%, a diagnosis of unclassifiable B-cell lymphoma is given with features in between DLBCL and BL." (PMID 33816589, 2021). "Double hit lymphoma (DHL)/THL refer to B‐cell lymphoma with MYC accompanied with Bcl‐2 and/or Bcl‐6 gene rearrangements." (PMID 34698437, 2021). "Due to their ability to intrinsic apoptosis signaling, recent reports demonstrate synergistic activity of BET inhibitors and the small-molecule BCL-2 inhibitor ABT199/venetoclax in killing MYC-driven B-cell lymphoma cells." (PMID 34298819, 2021). "MYC/BCL2/BCL6 triple-hit lymphoma (THL) is an uncommon subset of high-grade B-cell lymphoma with aggressive clinical behavior and poor prognosis." (PMID 34113336, 2021). "Therapeutic study in 30 DLBCL cell lines with various molecular and genetic background found robust cytotoxicity of selinexor, especially in cells with BCL2-rearranged (BCL2-R+) DLBCL or high-grade B-cell lymphoma with MYC/BCL2 double-hit (HGBCL-DH)." (PMID 33148342, 2020). "Further analyses revealed that alteration of the expression of signature genes by ColXV was associated with B-cell lymphoma family and ECM remodeling, especially Bcl-2, Col1a1, Col6a1, MMP-2 and MMP-9." (PMID 32024006, 2020). "Venetoclax (ABT-199), an oral first-in-class BCL2 inhibitor, showed antitumor activity in B-cell lymphoma." (PMID 32455989, 2020). "On the other hand, Fibronectin obtained an anti-apoptotic effect via Bcl-2 (B-cell lymphoma) in cancer." (PMID 32560557, 2020). "The BCL-2 protein (B cell lymphoma) is a product of the BCL-2 gene located on chromosome 18 at the 18q21.3 locus." (PMID 32366004, 2020). "A recent pre-clinical study shows that tigecycline combined with venetoclax promotes the primary response of MYC/BCL2 double-hit B cell lymphoma cells to rituximab-based chemoimmunotherapeutic regimens, also known as R-CHOP." (PMID 31336613, 2019). "RAC1 interacts with BCL2 (a co-localization and physical interaction between the two proteins) at the mitochondrial membrane of BCL2-overexpressing B-cell lymphoma cells, which stabilizes the anti-apoptotic, BCL2-mediated superoxide production." (PMID 31027363, 2019). "The apoptotic activity of BCL2L11 is frequently suppressed in B-cell lymphomas by overexpression of interacting factors like BCL2." (PMID 31141539, 2019). "BCL2 contributes to the pathogenesis of DLBCL by promoting the survival of B cells, as BCL2-transgenic mice have B cells with extended survival and these mice spontaneously develop aggressive B cell lymphoma." (PMID 30881917, 2019). "The anti-apoptotic effect of Rapamycin observed in B-cell lymphoma lines is reported to depend on upregulation of Bcl-2 on protein level." (PMID 31191530, 2019). "The BCL2 gene is involved in apoptosis and its co-expression with the oncogene MYC is associated with a poor prognosis in B-cell lymphoma patients." (PMID 30866419, 2019). "For B-cell lymphoma lines, Rapamycin increased Bcl-2 on protein level and moreover led to partial resistance to Fas-induced apoptosis." (PMID 31191530, 2019). "Meanwhile, MYC activation sensitizes MYC/BCL2 double-hit B cell lymphoma cells to inhibition of mitochondrial translation by the antibiotic tigecycline." (PMID 31336613, 2019). "Following the initial discovery of BCL-2 in the context of B-cell lymphoma in the 1980s, a number of homologous proteins have since been identified." (PMID 30792387, 2019). "BCL2 transgenic cohorts yielded a higher proportion of CD19+ B cell lymphomas compared to wild-type mice, most notably in the Vav-BCL2 cohort." (PMID 29985390, 2018). "It is noteworthy that many of the B cell lymphomas arising in the TRAF3/BCL2 double-tg mice show a nuclear localization of TRAF3." (PMID 30687320, 2018). "Bcl-2 knockout mice showed that Bcl-2 is required for normal B cells to survive, providing evidence for why B cell lymphomas would select for its overexpression." (PMID 30671383, 2018).
B-cell lymphoma (continued). "Of note, ectopic overexpression of BCL-2 in B cell lymphoma cell lines protects from ABT-263 (navitoclax)-induced death in vitro." (PMID 30671383, 2018). "The requirements of BCL-2 in the continued survival of human B cell lymphomas is just now being explored with some surprising results." (PMID 30671383, 2018). "To fully exploit the potential of selective inhibitors of anti-apoptotic BCL-2 proteins for the treatment of B cell lymphoma, we must know which inhibitors should be given to which patients." (PMID 30671383, 2018). "In this report, we show that TRAF3 and BCL2 cooperate to promote development of a variety of mature B cell lymphomas arising from antigen-challenged B cells." (PMID 30687320, 2018). "As a newly developed bio-therapeutic agent, ABT-199 is a specific Bcl-2 inhibitor targeting the BH3-binding domains of Bcl-2 and has demonstrated encouraging preclinical results in treating B-cell lymphoma." (PMID 28637496, 2017). "Bcl-2 is widely known to be an antiapoptotic proto-oncogene involved in carcinogenesis and is currently assessed for its use as a therapeutic target for B cell non-Hodgkin’s lymphoma." (PMID 28662697, 2017). "Altogether, our data show that 9-ING-41 results in increased apoptosis and decreased proliferation in aggressive B-cell lymphoma cells and enhances the antitumor effects of BCL-2 and CDK-9 antagonists." (PMID 29383130, 2017). "Among them, miR21 can target Bcl-2 expression by binding to Bcl-2 3’-untranslated region (610–617 bp) and stably expressed in peripheral blood and closely related to disease outcome in B-cell lymphoma as previously reported." (PMID 28637496, 2017). "miR-124 can suppress the fitness of B-cell lymphomas by targeting MYC and BCL2, which are coexpressed in B-cell lymphomas and associated with the poor prognosis." (PMID 27757114, 2016). "The designation double-hit lymphoma (DHL) has been used for a B-cell lymphoma carrying a MYC/8q24 rearrangement in combination with a rearrangement involving either BCL2, BCL6, or rarely other known oncogenes." (PMID 26573234, 2016). "Follicular lymphoma (FL) is a low-grade B cell lymphoma that has a translocation involving BCL2 in up to 90 % of cases, resulting in BCL2 upregulation." (PMID 26949422, 2016). "In the literature B-cell lymphomas with concurrent MYC/BCL2 or MYC/BCL6 rearrangements are grouped together as double-hit B-cell lymphomas." (PMID 26573234, 2016). "There were 49 patients with MYC/BCL2 DHL who had a history of FL (n = 46) or other type of low-grade non-Hodgkin B cell lymphoma (n = 3)." (PMID 27203548, 2016). "ABT-199 (venetoclax), a second-generation orally available derivative of ABT-737 that selectively targets BCL2 is currently under evaluation in clinical trials of B-cell NHL." (PMID 26654227, 2015). "The incidence and prognostic role of MYC and BCL2 rearrangements in mature B-cell lymphomas have been extensively studied, except the infrequent mantle cell lymphoma (MCL)." (PMID 26517511, 2015). "Genetic translocation affecting proto-oncogenes, such as Bcl2, Bcl6 or c-Myc, are found in many tumours, including follicular B-cell lymphoma, Burkitt lymphoma and “double hit” (DH) mature B cell lymphomas." (PMID 25680182, 2015). "Instead, combination treatment with I-BET762 and obatoclax, a small-molecule inhibitor of a wide number of Bcl-2 proapoptotic family members, restored apoptosis in Raji-4RH and RL-4RH B-cell lymphomas." (PMID 26658189, 2015). "Bcl-2 is the acronym for the B-cell lymphoma/leukemia-2, and as its name implies the gene was first discovered in B-cell malignancies." (PMID 26430964, 2015). "Expression of cluster 4 miRNAs are regulated by E2F1, can directly target BCL2/11/Bim to supress Myc-induced B cell lymphoma genesis and regulate several genes in the TGF-β pathway." (PMID 25330373, 2014).
B-cell lymphoma (continued). "Concordantly, anti-apoptotic Bcl2, which is found in BN25 6 and protects against endoplasmic reticulum stress, is at its highest level in P2, and has been associated with B-cell lymphomas and other cancers." (PMID 25004123, 2014). "Higher expression of the anti-apoptotic protein BCL-2 is more common in B-cell NHL than T-cell NHL and is heterogeneously expressed among the different histological subtypes." (PMID 25362242, 2014). "Originally identified as a chromosomal translocation in B-cell lymphoma, BCL-2 is the founding member of the family that is responsible for directly inhibiting the mitochondrial pathway of apoptosis." (PMID 25621172, 2014). "The 26 kDa Bcl-2 anti-apoptotic protein belongs to the Bcl-2 family of proteins, which was originally found to be overexpressed in B-cell lymphoma." (PMID 23324128, 2013). "Distinction between different types of B-cell lymphoma, pseudo-B-cell lymphoma, and secondary cutaneous B-cell lymphoma is made using Bcl-2, Bcl-6, CD10, MUM-1, and FOXP1." (PMID 29147306, 2012). "Consistent with the sensitivity of BCL-2 overexpressing MCF10A cells to ABT-737, we found that B-cell lymphoma cells with relatively high BCL-2 levels (SP53 and JeKo-1 cells) were also ABT-737 sensitive." (PMID 22880001, 2012). "Her spleen contained massive amount of CD20+/BCL-2+ B cells within the red and white pulp mimicking B-cell lymphoma." (PMID 22901769, 2012). "Cellular Bcl-2 was originally discovered as an oncogenic protein in B-cell lymphomas, since then a number of proteins belonging to the Bcl-2 family have been identified, each possessing the signature of Bcl-2 homology domain (BH)." (PMID 19816569, 2009). "Together, these findings suggest that proteasome and Bcl-2 inhibition may act additively in some B-cell lymphoma models." (PMID 40701968, 2025). "Of major concern are B-cell lymphomas, importantly extranodal marginal zone lymphoma of mucosa-associated lymphoid tissue, especially when monotypic plasmacytic differentiation occurs, and follicular lymphoma (in most cases CD10(+) and BCL-2 (+))." (PMID 40296965, 2025). "Recurrent gene fusions and chromosomal rearrangements involving MYC, BCL2, and BCL6 are hallmark genetic events in DLBCL and are defining features of specific DLBCL subtypes and high-grade B-cell lymphomas (HGBCL), as per the World Health Organization (WHO) 2016 and 2022 classifications." (PMID 41010038, 2025). "Although iTCL-GI is less reliant on Bcl-2 compared to B-cell lymphoma, therapeutic strategies targeting Bcl-2 could be effective in sustaining disease remission in selected patients." (PMID 40666527, 2025). "By investigation of a spectrum of TdT‐positive B‐cell lymphomas including DLBCL/HGBCL‐MYC/BCL2, DLBCL‐NOS, HGBCL‐NOS, B‐ALL/LBLs, and cases unclassified, the present study has highlighted several points that would aid the differential diagnosis between TdT‐positive DLBCL/HGBCL and B‐ALL/LBL." (PMID 41047873, 2025). "With the development of technology, a great many targeted drugs (BCL2 inhibitor, the histone deacetylas inhibitor, immunmodulator lenalidomide, obinutuzumab, phosphatidylinositol 3-kinase inhibitor, etc.)emerge and benefit B-cell lymphoma patients." (PMID 40418267, 2025). "Notably, some types of B-cell lymphoma show overexpression of Bcl-2, providing solid evidence that cell death dysregulation contributes to cancer development." (PMID 39005939, 2024). "Given the characteristics of mildly elevated cerebrospinal fluid protein levels, lymph node histopathology, Myc and BCL-6 rearrangement detected by standard cytogenetics, and weak Bcl-2 positivity, the disease is consistent with a diagnosis of high-grade B-cell lymphoma." (PMID 39969355, 2024). "HgCl2 group revealed reduced reactivity with histochemical and immunohistochemical stains (Masson’s Trichrome and B cell Lymphoma 2) when compared to the control, with a significant decrease in quantified liver Bcl-2 stain intensity when compared to the silymarin-treated group." (PMID 38641806, 2024).
B-cell lymphoma (continued). "Taking into account their variable morphology but homogeneous biological features and gene expression patterns, “double hit” cases with dual MYC and BCL2 rearrangements are designated diffuse large B-cell lymphoma/high-grade B-cell lymphoma with MYC and BCL2 rearrangements (DLBCL/HGBL-MYC/BCL2)." (PMID 38835969, 2024). "Overexpression of the anti-apoptotic protein BCL-2 provides a survival advantage to malignant B cells and is involved in malignant B cell tumorigenesis, disease progression, and chemoresistance, making BCL-2 a potentially important therapeutic target for B -cell NHL." (PMID 38333686, 2024). "Despite the non-B cell-restricted BCL2 expression in the VavP-BCL2 model, these mice develop clonal, somatically Ighv-mutated B cell lymphomas, which display a follicular growth pattern, as well as PNA and BCL6 expression and lack of post-GC markers." (PMID 38124747, 2023). "As overexpression of Bcl-2 leads to the failure of apoptosis of B lymphocytes in mice and also certain human B-cell lymphomas, we hypothesize that increased Bcl-2 expression in CAO samples prevents immune cell death." (PMID 37047053, 2023). "To date, a number of biomarkers with a diagnostic value for each B-cell lymphoma subtype have been determined: BCL2, BCL6, CD10, CD21, and STMN1 in FL; D1 and SOX11 in MCL; FOXP1 and MUM1 in ABC-DLBCL; CD10, BCL2, BCL6, LMO2, and GCET1 in GC-DLBCL; and CD30, CD15, EBV, BOB1, OCT2, and CD79a in HL." (PMID 37894763, 2023). "Additionally, we chose to look at BCL2 transcript stability as ZFP36L1 has been shown in B cell lymphoma to negatively regulate BCL2 transcript stability." (PMID 36376377, 2023). "Among them, DT2216 has entered the clinical stage and with the best prospects, which targets B-cell lymphoma/leukemia-xL (Bcl-xL) to the VHL E3 ligase for degradation, thereby inhibiting the anti-apoptotic function of the B-cell lymphoma/leukemia-2 (Bcl-2) family." (PMID 38174069, 2023). "Overexpression of anti-apoptotic molecule Bcl-2 is a hallmark of CLL and B cell lymphomas." (PMID 35897737, 2022). "Other mutation hot-spots in B-cell lymphoma were the enhancers of BCL6, BCL2 and ST6GAL1." (PMID 34210001, 2021). "As a protein highly expressed in a number of B-cell lymphomas, Bcl-2 is expressed in Chronic lymphocytic leukaemia (CLL), Mantle cell lymphoma (MCL), Multiple myeloma (t11;14) (MM) or solid tumors, and (in a similar manner to Mcl1 expression) is critical for cell survival." (PMID 34753495, 2021). "MYD88 mutations in the MCD/C5 ABC-DLBCL often occur in combination with BCL2 copy number gains, and indeed, in the Myd88L252P mouse model, the combination with Cd19-Cre driven overexpression of BCL2 led to a significant increase in ABC-DLBCL-like B cell lymphomas." (PMID 34456919, 2021). "Bcl-2 gene, namely B cell lymphoma/leukemia-2 gene, has the effect of inhibiting apoptosis." (PMID 32085781, 2020). "Overall, our data indicated that c-MYC and BCL2 Co-expression in GC B cells could induce B cell lymphoma." (PMID 32695674, 2020). "We show that Co-expression of c-MYC and BCL2 in germinal center (GC) B cells or pan-B cells could induce B cell lymphoma." (PMID 32695674, 2020). "We observed that Co-expression of c-MYC and BCL2 in germinal center B cells, or pan-B cells could both induce B cell lymphoma." (PMID 32695674, 2020). "In summary, these results illustrate that c-MYC and BCL2 Co-expression in pan-B cells could also induce B cell lymphoma." (PMID 32695674, 2020). "We observed that Co-expression of c-MYC and BCL2 in germinal center (GC) B cells, or pan-B cells could induce B cell lymphomas." (PMID 32695674, 2020). "We found that Co-expression of c-MYC and BCL2 in germinal center B cells could induce B cell lymphoma." (PMID 32695674, 2020).
B-cell lymphoma (continued). "The crucial role of CD37 in B cell lymphoma formation comes from a murine model, where CD37-deficient mice spontaneously developed germinal center–derived B cell lymphoma in lymph nodes and spleens with a higher incidence than Bcl2 transgenic mice (50% vs. 20%)." (PMID 33333768, 2020). "The BCL-2 inhibitor venetoclax was more sensitive in HMCLs and B-cell NHL than in T-cell NHL." (PMID 32393731, 2020). "Indeed, high-grade B-cell lymphomas with chromosomal breakpoints affecting the MYC locus in combination with breakpoints involving the BCL2 or BCL6 genes, constitute a separate entity frequently called “DH lymphomas”1." (PMID 30926794, 2019). "BCL-2 was the first member of the family to be identified, due to its role in B-cell lymphoma." (PMID 30792387, 2019). "Bcl-6, IRF-4 (MUM-1) and Bcl-2 were often detected in patients with HBsAg-positive B-cell NHL." (PMID 31120924, 2019). "But the recognition of DLBCL with MYC and/or BCL2 overexpression could be used to expand the spectrum of aggressive B-cell lymphomas and effective stratify patients." (PMID 29674626, 2018). "Lastly, given the heterogeneity among entities (molecular subgroups, aggressiveness, tissue), this ratio could help predicting the B cell lymphoma patients who would benefit to BCL2 specific BH3-mimetic based therapy." (PMID 30666297, 2018). "To identify candidates most likely to cause disease, we searched for additional evidence in the literature supporting the role of candidate genes in hematologic malignancies, with an emphasis on data from human lymphoid malignancies and a particular focus on BCL2-driven B cell lymphoma." (PMID 29985390, 2018). "Bcl-2 can be extracted from B cell lymphoma and present a distinct capacity of antiapoptosis." (PMID 27556046, 2016). "Preclinical and early clinical studies demonstrated that ABT-199 inhibits the growth of aggressive c-MYC-driven mouse B-cell lymphomas and human BCL2-dependent B-cell lymphoma tumors in vivo without causing thrombocytopenia." (PMID 26654227, 2015). "Notably, a strong correlation between the expression and/or phosphorylation of STAT3 and Bcl-2 was observed in primary tissues derived from patients with different sub-sets of B cell lymphoma." (PMID 26430964, 2015). "Interestingly, a strong correlation between STAT3pSer727 and total Bcl-2 levels was observed in large B-cell lymphomas (N = 6) with a correlation coefficient of +0.9339." (PMID 26430964, 2015). "We have shown that our parametric model can be applied to aggressive as well as indolent clones of B-cell lymphomas, and that it can predict the efficacy of a combination of anti-Bcl-2 ABT-263, a predecessor drug to ABT-199, and anti-CD-20 rituximab in the absence of an immune system." (PMID 26068800, 2015). "Bcl-2 was initially isolated and characterized in a subset of B-cell lymphomas." (PMID 22683550, 2012). "The initial diagnostic approach of aggressive peripheral B-cell lymphomas should include the evaluation of the morphological and immunophenotypic characteristics including, as previously discussed, the COO and the percentage of MYC and BCL2-positive neoplastic cells." (PMID 39684922, 2024). "Finally, in a recent study involving 40 T-cell AL, 5 B-cell AL and 8 IBD, T-cell lymphomas in particular were characterised by a high percentage of Bcl-2 (B-cell lymphoma gene 2) labelled cells, whilst B-cell lymphomas varied more widely in the number of positively-labelled cells." (PMID 30305106, 2018). "Therefore, the low co-expression of BCL2/MYC in our series of cases could explain our observation of the favorable prognosis of B-cell lymphomas involving WR." (PMID 28086220, 2017).